MAPT (microtubule associated protein tau)
Diseases named in the same sentence as MAPT in open-access papers (continued):
Sharing a sentence is not in itself a finding about the gene and the disease.
Onset (4 papers, 2009 to 2025). The age group in which disease manifestations appear. "Genetic association of MAPT variants with late-onset AD (LOAD) risk has been inconsistent, although insufficient power and incomplete assessment of MAPT haplotypes may account for this." (PMID 25324900, 2014). "Patients with spinal onset ALS showed greater elevation of pTau181, pTau217, pTau231, and MAPT as compared to bulbar onset disease, agreeing with previous data showing higher pTau181 in spinal onset ALS." (PMID 39913612, 2025).
parkinsonian disorder (4 papers, 2017 to 2023). A group of disorders which feature impaired motor control characterized by bradykinesia, MUSCLE RIGIDITY; TREMOR; and postural instability. "For example, the alternatively spliced gene encoding microtubule-associated protein tau (MAPT) contains several mutations that are involved in the pathogenesis of Parkinsonian disorders located in introns up to 47 kb away from downstream or upstream exonic sequences." (PMID 34083785, 2021). "Interestingly, a variant with strong association with parkinsonian disorders was found to decrease NRF2 binding at an ARE in the intron of the Microtubule Associated Protein Tau (MAPT) gene and to drive lower MAPT transcription in neuronal progenitors." (PMID 35892629, 2022).
spinal muscular atrophy (4 papers, 2014 to 2021). A motor neuron disease that affect the muscles, and characterized by muscle weakness and atrophy resulting from progressive degeneration and irreversible loss of the anterior horn cells in the spinal cord (i.e., lower motor neurons) and the brain stem nuclei. "Several model systems have shown hnRNP G to be a key modulator of alternative splicing in multiple genes implicated in neurogenerative disease including SMN2 in spinal muscular atrophy and microtubule-associated protein tau (MAPT) in FTLD." (PMID 32748079, 2020).
Cerebral ischemia (3 papers, 2021 to 2022). Restriction of arterial blood supply to the brain associated with insufficient oxygenation to support the metabolic requirements of the tissue. "Researchers have found that brain ischemia/reperfusion (CIR) animal models have high abnormally hyperphosphorylated MAPT, which is closely linked to neurological deficits and neuronal apoptosis." (PMID 36105479, 2022). "Studies have revealed that a large number of abnormal hyperphosphorylated MAPT exists in cerebral ischemia/reperfusion (CIR) animal models, which is closely related to neuronal apoptosis and neurological deficits." (PMID 33841157, 2021). "•The present study preliminarily showed that regulating SIRT1 can further affect MAPT protein, providing a new idea to the pathogenesis of cerebral ischemia." (PMID 33841157, 2021).
cortical atrophy (3 papers, 2020 to 2025). "Further studies are needed to characterize the trajectories of rates of cortical atrophy across the different subtypes of MAPT mutations." (PMID 32184751, 2020). "Our analysis revealed distinct sets of PLS1 genes positively or negatively associated with cortical atrophy for C9orf72-bvFTD, GRN-bvFTD, and MAPT-bvFTD, potentially reflecting molecular mechanisms underlying neuroanatomical changes." (PMID 39920674, 2025). "Recently, two longitudinal studies from a cohort of asymptomatic MAPT mutation carriers have reported that hippocampal volumes decline during a 2-year follow-up, but no cortical atrophy was found in longitudinal analysis with 4 years of follow-up." (PMID 32184751, 2020).
developmental delay (3 papers, 2012 to 2021). "The phenotypic profile of MAPT IVS10+16 neurons could not be explained by a developmental delay due to the introduced mutation." (PMID 34274950, 2021).
Dystonia (3 papers, 2021 to 2025). An abnormally increased muscular tone that causes fixed abnormal postures. "Among the different genetic forms of CBS, carriers of MAPT mutations exhibit the highest prevalence of tremor, dystonia, and oculomotor dysfunction, highlighting the pervasive presence of motor deficits." (PMID 40722695, 2025).
lung adenocarcinoma (3 papers, 2022 to 2025). A carcinoma that arises from the lung and is characterized by the presence of malignant glandular epithelial cells. "Furthermore, we have found that the mRNA levels of SEPT9 and HIST1H2BH were higher in tumor tissue in comparison with adjacent tissue in 30 lung adenocarcinoma patients and lower in MAPT." (PMID 34854250, 2022).
lung carcinoma (3 papers, 2020 to 2023). "Resistance to MEK inhibitors correlated positively with MAPT for cell lines derived from breast and lung cancer, and negatively for skin-derived cell lines." (PMID 37730697, 2023). "MAPT has been shown to induce lung cancer cells to gain taxol resistance by activating the PI3K/Akt signaling pathway." (PMID 37189139, 2023). "Predicted expression of seven genes was significantly (p < 5.0 × 10−4) associated with lung cancer risk: SECISBP2L, HLA-L, DISP2, MAPT, KANSL1-AS1, LRRC37A4P, and PLEKHM1." (PMID 31911640, 2020).
myotonic dystrophy type 1 (3 papers, 2023 to 2025). Steinert disease, also known as myotonic dystrophy type 1, is a muscle disease characterized by myotonia and by multiorgan damage that combines various degrees of muscle weakness, arrhythmia and/or cardiac conduction disorders, cataract, endocrine damage, sleep disorders and baldness. "In myotonic dystrophy type 1 (DM1), however, aberrant MAPT splicing has been documented at multiple exons—including exon 10 as well as exons 2/3 and 6—resulting in an altered 3R/4R ratio, often with a relative predominance of the 3R isoform." (PMID 41303231, 2025).
Neurofibrillary tangles (3 papers, 2018 to 2022). Pathological protein aggregates formed by hyperphosphorylation of a microtubule-associated protein known as tau, causing it to aggregate in an insoluble form. "Neurofibrillary tangle (NFT) caused by abnormally phosphorylated Tau proteins (encoded by MAPT gene) is one of the classic pathological hallmarks of AD." (PMID 35662233, 2022).
neuropathy (3 papers, 2014 to 2025). A disorder affecting the nervous system that manifests with pain, tingling, numbness, and/or muscle weakness. "Regarding rs7001034 in the FZD3 gene and rs242557 in the MAPT gene, an association with neurotoxicity was observed, in particular allele A increased the occurrence of ineuropathy, although it was not confirmed for severe neuropathy." (PMID 36307826, 2022). "The present study examined the potential effects of MAPT haplotype, expression levels, and GSK-3β mediated tau phosphorylation on the development of paclitaxel-induced neuropathy in vivo." (PMID 25535399, 2014).
Obesity (3 papers, 2021 to 2023). Accumulation of substantial excess body fat. "Besides this encouraging case, we also find a surprising case concerning Lansoprazole, a drug that targets MAPT, a gene shared by the multimorbidity of E66 (Obesity) and J84 (Other interstitial pulmonary diseases)." (PMID 34225788, 2021).
psoriasis (3 papers, 2019 to 2024). An autoimmune condition characterized by red, well-delineated plaques with silvery scales that are usually on the extensor surfaces and scalp. "The median serum MAPT concentration in patients with psoriasis was 22.35 pg/mL before treatment and was significantly higher compared to the controls: 16.55 pg/mL (p < 0.05)." (PMID 36078974, 2022). "Serum concentrations of tau protein (MAPT), neuronal cell adhesion molecule (NrCAM) and neprilysin (NEP), which are NDs biomarkers and have been hardly studied in psoriasis before, were measured before and after 12 weeks of treatment with acitretin or methotrexate." (PMID 36078974, 2022). "Serum MAPT level did not correlate with psoriasis severity expressed with PASI score, nor BMI, both before and after therapy (all p > 0.05)." (PMID 36078974, 2022).
amnesia (2 papers, 2014 to 2024). Pathologic partial or complete loss of the ability to recall past experiences ( AMNESIA, RETROGRADE) or to form new memories ( AMNESIA, ANTEROGRADE). "The presence of amnesia as an initial symptom in one individual emphasizes clinical heterogeneity, even within families carrying the same MAPT variants." (PMID 38708005, 2024). "Our case illustrates this point and the importance of screening for MAPT mutations in families with an autosomal dominant history of an amnestic syndrome where mutations for familial AD have proven negative." (PMID 23998300, 2014).
Apathy (2 papers, 2023 to 2025). Apathy is a quantitative reduction of interest, motivation and the initiation and persistence of goal-directed behavior, where often the accompanying emotions, thoughts, and social interactions are also diminished. "Progranulin (PGRN) mutations correlated with apathy and hallucinations, microtubule-associated protein tau (MAPT) mutations with disinhibition, and charged multivesicular body protein 2B (CHMP2B) with social impairments." (PMID 40649976, 2025). "The patient carrying PRKN deletion of exon 4, LRRK2 deletion of exon 49, and MAPT p.Asn596Lys had dominant motor disturbances (high MDS‐UPDRS score of part III), but without the presence of apathy as previously reported." (PMID 36879366, 2023).
behavioral disorder (2 papers, 2019 to 2024). "Taking into account that R406W MAPT mutation has also been associated with slowly progressive behavioral disorder, the genetic screening for this mutation must also be considered in selected cases." (PMID 30935398, 2019).
bone cancer (2 papers, 2023 to 2024). A primary or metastatic malignant neoplasm affecting the bone or articular cartilage. "In bone cancer cell lines, high MAPT expression was observed to be linked with a positive response to kinase inhibitors (Aurora, PI3K), HDAC inhibitors as well as DNA damaging drugs." (PMID 37730697, 2023). "Tau (MAPT) is expressed in various isoforms in neurons and bone cancer; its function is in microtubule stabilization and polarization." (PMID 39518906, 2024). "While cells derived from uterine and bone cancers were the ones with the higher number of drugs correlated with MAPT expression, only a few drugs did the same for cell lines derived from tumors affecting tissues such as the CNS, colorectal, upper aerodigestive, blood, and esophagus." (PMID 37730697, 2023). "A negative correlation between MAPT expression and resistance to several drugs with various modes of action is detected in pancreatic, uterine, and mainly bone cancer-derived cell lines, whereas predominantly positive correlations were found in cell lines derived from other cancers." (PMID 37730697, 2023).
brain cancer (2 papers, 2019 to 2023). A primary or metastatic malignant neoplasm affecting the brain. "Substantial differences in cell lines derived from prostate and brain cancers suggest that MAPT phosphorylation might strongly depend on the tumor type." (PMID 30823906, 2019).
brain injury (2 papers, 2022). Acute and chronic (see also brain INJURIES, CHRONIC) injuries to the brain, including the cerebral hemispheres, CEREBELLUM, and brain STEM. "Nevertheless, epistasis analysis identified a genetic interaction of COMT (rs4680) and MAPT (rs10445337) G-C alleles as more common in elite rugby athletes, and carriage of these variants may affect stress resilience, behavioural traits and altered risk of concussion incidence and severity." (PMID 35627205, 2022).
brain tumors (2 papers, 2022 to 2023). "Importantly, genes downregulated after MAPT KO had a positive association with MAPT in brain tumors (GBM, PCPG, LGG) and vice versa for upregulated genes." (PMID 37730697, 2023).
Cerebellar atrophy (2 papers, 2013 to 2021). Cerebellar atrophy is defined as a cerebellum with initially normal structures, in a posterior fossa with normal size, which displays enlarged fissures (interfolial spaces) in comparison to the foliae secondary to loss of tissue. "The cerebellum was also affected in mutant mice, and it has been shown that cerebellar atrophy occurs in both mutant C9orf72 and MAPT associated FTD." (PMID 34136812, 2021). "In fact, c9FTD is characterized by greater cerebellar atrophy than sporadic FTD, as well as FTD caused by mutations in MAPT." (PMID 24129584, 2013).
cerebral amyloid angiopathy (2 papers, 2021 to 2023). "Altered deposition of microtubule-associated protein tau (tau pathology) and accumulation of Aβ (cerebral amyloid angiopathy) within or adjacent to BCECs induces a loss of vascular function in LOAD." (PMID 37907966, 2023).
Delusion (2 papers, 2021 to 2023). A delusion is a fixed false belief held despite evidence to the contrary. "Although less common than affective symptoms, ‘psychosis’ features, that is, hallucinations and delusions occur in up to a quarter of symptomatic patients, and more frequently in C9orf72 than GRN and MAPT mutation carriers." (PMID 36627201, 2023).
essential tremor (2 papers, 2022 to 2024). A relatively common disorder characterized by a fairly specific pattern of tremors which are most prominent in the upper extremities and neck, inducing titubations of the head. "MAPT H1 haplotype is a risk factor for the incidence of essential tremor." (PMID 36258958, 2022).
hepatocellular carcinoma (2 papers, 2019 to 2021). A malignant tumor that arises from hepatocytes. "In the intragenic region, MAPT-int1AS (CATG00000033807.1) is almost exclusively expressed in the liver and in hepatocellular carcinoma cell lines HepG2, while MAPT-int2AS (CATG00000033811.1), albeit annotated, cannot be measured after stringent cutoff." (PMID 30610612, 2019).
infarction (2 papers, 2021 to 2022). A localised pathological necrosis of tissue resulting from obstruction of the blood supply usually by a thrombus, an embolus, or vascular torsion. "By upregulating SIRT1 expression, AS-IV decreases acetylated MAPT (ac-MAPT) and phosphorylated MAPT (p-MAPT) levels, ultimately reducing infarction size and improving neurological function." (PMID 36105479, 2022). "The results of this study demonstrated that AS-IV can improve neurological dysfunction, decrease infarction area, upregulate the expression of SIRT1, and decline the levels of ac-MAPT and p-MAPT." (PMID 33841157, 2021).
kidney cancer (2 papers, 2021 to 2023). Primary or metastatic malignant neoplasm involving the kidney. "For example, low expression of MAPT was also associated with poor survival time and serve as a tumor suppressor in kidney cancer." (PMID 35252219, 2021). "At the same time, in some instances, very different cancer types (e.g. BRCA and kidney cancer) could be members of the same cluster, indicating an overall similarity in the way genes correlated with MAPT expression." (PMID 37730697, 2023).
language disorder (2 papers, 2016 to 2021). A category of disorders characterized by an impairment in the development of an individual's language capabilities, which is in contrast to his/her non-verbal intellect. "The fourth language disorder, lvPPA, did not share any of its four genes (APOE, APP, GRN, MAPT) with the other disorders." (PMID 34539327, 2021).
melanoma (2 papers, 2011 to 2022). A malignant, usually aggressive tumor composed of atypical, neoplastic melanocytes. "Microtubule-associated protein 2 (MAP2) has been shown to be a prognostic marker for melanoma patients, and splice variants of MAPT gene demonstrated opposite changes in normal versus prostate tumor." (PMID 21501490, 2011). "Our in silico analysis of IFN-treated melanoma tissues of TCGA revealed the differential expression of five members of our 79 IFN-res DEGs in IFN-treated melanoma tissues: IRG SOX4 and non-IRGs WFDC1, BCAN, RPE65, and MAPT." (PMID 35269844, 2022).
microcephaly (2 papers, 2014 to 2015). A congenital or acquired developmental disorder in which the circumference of the head is smaller than normal for the person's age and sex. "Other genes within the combined network are involved in neuronal progenitor cell proliferation, a common mechanism underlying microcephaly (RAC1 and GNB1) and neuronal development (CEBPB, L1CAM, MAPT, PAK2, SPTBN1, and YWHAE)." (PMID 25781962, 2015).
orthostatic hypotension (2 papers, 2020 to 2022). Sudden fall of the blood pressure of at least 20/10 mm Hg when a person stands up. "In conclusion, we found MAPT H1 subhaplotypes H1b, H1j, H1r, and H1v were associated with an altered risk for specific clinical features in patients with PD, including orthostatic hypotension, tremor at rest, RBD, bradykinesia, and RLS." (PMID 32767721, 2020).
Pancreatic cancer (2 papers, 2020 to 2025). "In pancreatic cancer, MAPT has been recognized as a predictive marker of the treatment effect of sulfur benzoylphenylurea analogs (SG410 and SG430), and the methylation of MAPT in plasma has been detected for the noninvasive diagnosis of pancreatic cancer." (PMID 40836964, 2025). "In the present study, a hypoxia- and immune-associated prognostic signature, which included 6 genes (GALR2, AGT, MAPT, PRKCG, CAMK2B, and PKP1), was established via LASSO Cox regression in patients with pancreatic cancer from the TCGA dataset and was further validated in 2 independent GEO datasets." (PMID 40836964, 2025). "It suggested that the eight markers: MAPT, SIX3, MIR663, EPB41L3, FAM150A, TRIM73, LOC100128977, and LOC100130148 may serve as potential biomarkers for the early diagnosis of pancreatic cancer." (PMID 33424927, 2020). "Pancreatic cancer patients with a high expression of MAPT, EPB41L3, LOC100128977, and LOC100130148 had an evidently higher overall survival as compared with those with a low expression of MAPT (p = 0.0034), EPB41L3 (p = 0.0088), LOC100128977 (p = 0.0077), and LOC100130148 (p = 0.0017)." (PMID 33424927, 2020). "However, the multivariate Cox regression analysis indicated that TRIM73, FAM150A, EPB41L3, SIX3, MAPT, LOC100128977, and LOC100130148 might not be independent factors for the prognosis of pancreatic cancer patients." (PMID 33424927, 2020).
Peri-Implantitis (2 papers, 2019 to 2022). An inflammatory process with loss of supporting bone in the tissues surrounding functioning DENTAL IMPLANTS. "MAPT, GZMK, and SOSTDC1 were highly correlated with high abundance of immune cells, possibly reflecting immune cell perturbations accompany ageing-associated signalling pathways to play a role in peri-implantitis lesions in aged tissues." (PMID 36267464, 2022). "Three leader genes (PSMD10, SOS1, WASF3), eight cross-talk genes (PSMD10, PSMD6, EIF2S1, GSTP1, DNAJC3, SEC61A1, MAPT, and NME1), and one signaling pathway (IL-17 signaling) emerged as peri-implantitis and T2DM linkage mechanisms." (PMID 31275749, 2019).
Postural instability (2 papers, 2023 to 2024). A tendency to fall or the inability to keep oneself from falling; imbalance. "The predominance of postural instability as the initial symptom in this family aligns with observations from the broader PSP population with MAPT variants." (PMID 38708005, 2024).
autoimmune thyroid disease (1 paper, 2021). Inflammatory disease of the thyroid gland due to autoimmune responses leading to lymphocytic infiltration of the gland. "MAPT was related to ‘antigen processing and presentation’, ‘natural killer cell-mediated cytotoxicity’, ‘autoimmune thyroid disease’, ‘cell adhesion molecules’, and the ‘proteasome’." (PMID 34406386, 2021).
Autoimmunity (1 paper, 2025). The occurrence of an immune reaction against the organism's own cells or tissues. "Beyond autoimmunity, our analysis identified genes with dual roles in AIDs and cancer, such as CDC37, DDX6, and MAPT, suggesting possible immune–oncogenic links." (PMID 40429780, 2025).